IL22 (interleukin 22)
Diseases named in the same sentence as IL22 in open-access papers (continued):
Sharing a sentence is not in itself a finding about the gene and the disease.
colitis (continued). "A recent study showed that mice fed a short course of a high-fat diet developed mild signs of colitis accompanied by impaired IL-22 production by enteric ILC3s." (PMID 40498001, 2025). "Modulating the Treg/Th2 response by decreasing proinflammatory cytokines such as TNFα, IL-6, IL-1β, IL-18, IL-22, IL-9 and increasing anti-inflammatory cytokines IL-10 and IL-4 in mice colitis model." (PMID 41208998, 2025). "AhR activation has been linked to the alleviation of colitis by reducing inflammatory cytokines like IL‐1β, IL‐6, and TNF‐α, while enhancing anti‐inflammatory cytokines, such as IL‐4, IL‐10, and IL‐22, and strengthening the intestinal epithelial barrier." (PMID 39836604, 2025). "Several studies have demonstrated that IL-22 promotes intestinal epithelial repair in DSS-induced colitis." (PMID 40243444, 2025). "KO of either C/EBPβ or STAT3 in colon epithelial cells abolished the protective functions of IL-17A and IL-22 against DSS-induced colitis." (PMID 40749055, 2025). "The commensal bacterium Akkermansia muciniphila stimulated DCs to produce retinoic acid, thereby reinforcing IL-22-mediated barrier function and mitigating colitis." (PMID 40498001, 2025). "Consistently, the spontaneous recovery of acute colitis is accompanied by upregulation in IL-22 expression, which leads to the restitution of goblet cells." (PMID 41467015, 2025). "A recent study found that apoptotic neutrophil-derived lysophosphatidylserine directly facilitates ILC3 activation and IL-22 production during experimental colitis." (PMID 41467015, 2025). "IL-22 is another protective TH17-produced cytokine that protects against chemically induced colitis and CRC." (PMID 40749055, 2025). "Here we investigate the protective role of IL-22 and hemopexin in the context of colitis using the dextran sodium sulphate (DSS) acute colitis model in mice." (PMID 40791589, 2025). "For example, Bao and colleagues recently demonstrated that, in a dextran sodium sulfate (DSS) mouse model of colitis, the exposure to bacterial sphingolipids leads to a reduced IL-22 secretion from ILC3s with consequent worsening of colitis." (PMID 40002718, 2025). "In a mouse model of TNBS-induced colitis, Higher levels of IL-22 were observed in dendritic cells (DCs) with AhR activation mediated by 6-formylindole [3,2-b] carbazole (FICZ)." (PMID 41019044, 2025). "Particularly, the direct administration of exogenous cytokines (IL-17A or IL-22) inhibits chemokine expression in the colon tissues and partially protects the mice against colitis, consistent with the resistant phenotypes observed in the chemokine KO mice." (PMID 40749055, 2025). "FBTP significantly increased the colonic expressions of aromatic hydrocarbon receptors (AhRs) and interleukin-22 (IL-22) and further promoted the expressions of intestinal tight junction (TJ) proteins ZO-1 and occludin in the colitis mice." (PMID 40238292, 2025). "We show that recombinant IL-22 administration significantly alleviated inflammation in DSS-treated mice while conversely, IL-22ra1 deficiency exacerbated colitis severity in DSS-treated mice." (PMID 40791589, 2025). "IL-22 inactivation in IBD mouse models significantly reduced colitis levels, correlating with diminished ER stress in the intestinal epithelium." (PMID 40429917, 2025). "Activation of the IRE1α/XBP1 signaling axis enhanced IL-22 production upon IL-23 stimulation and conferred protection against colitis." (PMID 40498001, 2025). "Vitamin C has also been shown to prevent DSS-induced colitis by regulating the production of IL-22 and IL-6 in mice." (PMID 40077487, 2025). "While T cells produce proinflammatory cytokines, which contribute to the induction of colitis, they also produce anti-inflammatory cytokines, including IL-10 and IL-22, which inhibit colitis development." (PMID 41321963, 2025).
colitis (continued). "We found that TH17 cells and their IL-17A and IL-22 render resistance to DSS-induced colitis and CRC development through blocking immune cell infiltration into the local epithelial tissues, which is associated with chemokine expression in epithelial tissues." (PMID 40749055, 2025). "Bacteroides ovatus-produced IAA stimulates the production of IL-22 by immune cells, exerting beneficial effects in colitis." (PMID 40225339, 2025). "Mice with Ire1α deletion in ILC3s (Ire1αΔRorc) showed reduced expression of the ER stress response and cytokine genes including Il22 in ILC3s and were highly vulnerable to infections and colitis." (PMID 38722686, 2024). "As we observed that Il22Ra1Math1-PGR mice are more susceptible to DSS-induced colitis, we explored the additional IEC target of IL-22 to induce regeneration in response to inflammation." (PMID 38733584, 2024). "Ire1αΔRorc mice were highly susceptible to colitis induced by C. difficile and C. rodentium as well as to DSS-induced colitis; the latter was attenuated by administration of exogenous IL-22." (PMID 38722686, 2024). "Card9 gene directly contributes to recovery from dextran sodium sulfate (DSS)-induced colitis by inducing the colonic expression of the cytokine IL-22 and the antimicrobial peptides Reg3β and Reg3γ independently of the microbiota." (PMID 38649950, 2024). "In contrast to the reported beneficial effects of IL‐22 in colitis, some studies using murine colitis models report that IL‐22 has a harmful role in the intestine." (PMID 38363052, 2024). "We previously reported that an aryl hydrocarbon receptor (AhR) ligand, indole-3-carbinol (I3C), was effective at reducing colitis severity through immune cell-mediated interleukin-22 (IL-22) production." (PMID 38397081, 2024). "AhR signaling upregulates IL-22 production to produce antimicrobial peptides and inhibit inflammation and colitis in the gastrointestinal tracts of mice." (PMID 38790988, 2024). "Our research results suggested that the expression level of IL-22 decreased in colitis, while after HnAg intervention, the IL-22 protein expression level increased." (PMID 39666730, 2024). "Regardless, our continued research in the area of I3C-mediated protective effects during colitis continues to identify IL-22 production by ILC3s as a major mechanism to be further explored." (PMID 39229279, 2024). "DSS-colitis represents an acute murine model of colitis in which cytokines of IL-17, IL-23, and IL-22 group are involved." (PMID 39354587, 2024). "IL-22 demonstrates rapid alleviation of local intestinal inflammation in a mouse model of Th2-mediated colitis resembling UC." (PMID 39767818, 2024). "This suggests that IL‐22 of both innate and adaptive origin had a protective role in this murine colitis model." (PMID 38363052, 2024). "NPM1 was abundant in ILC3s and was essential for IL-22 production in response to dextran sulfate sodium (DSS)-induced colitis." (PMID 39103576, 2024). "Although overexpression of Npm1 did not enhance the frequency of colonic ILC3s, a higher proportion were producing IL-22, indicating that Npm1OE enhanced the defense function of ILC3s against colitis." (PMID 39103576, 2024). "Alistipes finegoldii mediates protection from dextran sodium sulfate (DSS)-induced colitis by restoring intestinal barrier function through the enhanced colonic expression of intestinal IL-22 and Reg3γ." (PMID 38303112, 2024). "Consistently, the inability to alleviate colitis in IL-22-/- mice with RA alone or combined with Akk confirms IL-22’s essential role in RA-related mucosal repair." (PMID 39734222, 2024). "In line with this, by enhancing the secretion of IL-22, RA effectively mitigates colitis induced by dextran sulfate sodium (DSS)." (PMID 39734222, 2024). "By using genetic mice models, we identified two pathways by which IL-22 protects from colitis development." (PMID 38733584, 2024).
colitis (continued). "The same effect was observed in mice with knockout for IL-22: colitis was healed with the administration of IL-22." (PMID 38543132, 2024). "Like the phenotype observed in infectious diseases, multiple studies have reported a protective role of IL-22 in colitis induced by dextran sodium sulfate (DSS) treatment or adoptive transfer of naïve CD4+ T cells." (PMID 39379604, 2024). "Our work shows a novel interaction between gut microbiota and host immunity and the importance of RA-induced IL-22 in protecting against colitis by Akk." (PMID 39734222, 2024). "In an experiment with Il‐23‐/WTRag−/− mice, neutralization of endogenous IL‐22 with anti‐IL‐22 antibody after anti‐CD40 injections leads to a significant reduction in weight loss, colitis scores, and colon pathology." (PMID 38363052, 2024). "In a previous study, we showed that CARD9 mediates recovery from colitis through the production of IL-22, a cytokine with well-known effects on intestinal homeostasis and barrier function." (PMID 38649950, 2024). "Since other cytokines such as IL-20 and IL-24 also signal through IL-22Ra1, we used Il22−/− mice and observed that these mice were more susceptible to DSS-induced colitis as compared to wild-type controls." (PMID 38733584, 2024). "Wild-type mice also had higher expression of genes associated with inflammatory cytokines (Il6 and Il22) and transcription factors downstream of both toll-like receptor and PAR2 signaling (Stat3 and Bcl6), compared to R38E-PAR2 mice after colitis." (PMID 39171684, 2024). "CARD9 promotes recovery from colitis by promoting AhR ligands and IL-22 production.Host genes affect the composition and function of the gut microbiota, altering the production of microbial metabolites and intestinal inflammation." (PMID 39767818, 2024). "There is evidence showing decreased mucosal inflammation of the Bacteroides ovatus ATCC 8384 monotherapy in marine colitis model and promotion of IL‐22 production via dendritic cell differentiation." (PMID 39620016, 2024). "The key findings from the current report are AhR can regulate IL-22 signaling in specific cell types during colitis to alter the gut microbial profile which have consequential and sex-dependent impacts on disease severity." (PMID 39229279, 2024). "Studies on colitis suggest that activation of STAT3 signaling stimulated by IL-22 confers protective effects on the colonic mucosal immune system." (PMID 38732497, 2024). "These notions underscore the pivotal role of IL-22 in Akk’s protective response towards DSS-induced colitis." (PMID 39734222, 2024). "The total colitis score confirmed considerably higher inflammation in Il22−/− mice compared to WT mice." (PMID 38557196, 2024). "Administration of FICZ, a ligand of AHR can increase IL-22 expression that prevents and even heals colitis." (PMID 38542367, 2024). "It has been reported that the AhR ligand I3C is capable of increasing PPARγ expression in a TNBS-induced colitis model, leading to disease remission mediated by control of inflammation exerted by IL-22." (PMID 39684781, 2024). "In this study, we demonstrated that NPM1, a protein that is abundant in colonic ILC3s, is critical for the activation of IL-22 production in response to colitis." (PMID 39103576, 2024). "After DSS-induced colitis we detected statistically significant increases in IL-22 and IL-18 concentration and insignificant but clearly visible trend in increase of IL-6 and IL-12p40." (PMID 39354587, 2024). "On the other hand, Card9 is required for regulating the microbiota capacity to produce AhR ligands, which leads to the production of IL-22 in the colon, promoting recovery after colitis." (PMID 38649950, 2024). "For example, in a DSS-induced colitis model, IL-22, IL-17A, and GM-CSF play suppressive roles in colitis, suggesting their beneficial effects on IECs." (PMID 39379604, 2024).
colitis (continued). "In summary, our study highlights the role of NPM1 in maintaining mitochondrial function and IL-22 production in ILC3s in the progression of colitis." (PMID 39103576, 2024). "Results showed while there was a significant increase in IL-22 producing ILC3s for LM disease mice given I3C treatment (LM+Colitis+I3C) compared to their respective disease controls (LM+Colitis+Vehicle), AhRΔRorc mice failed to respond in a similar fashion." (PMID 39229279, 2024). "Several single‐cell studies have indicated that ILTC metabolism tends to shift towards FAO, which inhibits the release of the inflammatory regulator IL‐22, an initiating factor that increases the development of colitis following anti‐PD‐1 therapy." (PMID 38468489, 2024). "In the current study, we continued using I3C administration to determine AhR-mediated effects on colitis and regulation of the gut microbiome with focused attention on IL-22 production." (PMID 39229279, 2024). "Possible mechanisms by which IL‐22 can influence colitis is by inducing epithelial hyperplasia as there is evidence that IL‐22 promotes epithelial cell proliferation in the colon." (PMID 38363052, 2024). "Using germ-free models, we proved the direct contribution of Card9 gene in colitis recovery, through the induction of IL-22, REG3β, and REG3, independently of the microbiota." (PMID 38649950, 2024). "Our findings indicated that GPX4 mediated ILC3s, particularly the NKp46+ILC3 subpopulation, specifically regulating colitis, accompanied by alterations in ferroptosis characteristics of ILC3s and their secretion capacity for IL-22 and IL-17A." (PMID 39300068, 2024). "In the current study, we performed single-cell RNA sequencing (scRNAseq) from colonocytes during colitis induction and supplementation with I3C and show how this treatment alters expression of genes involved in IL-22 signaling." (PMID 39229279, 2024). "Conversely, excessive secretion of IL-17 and IL-22 can trigger an exaggerated neutrophil response, exacerbating barrier damage and contributing to colitis." (PMID 39300068, 2024). "For example, microbe-derived IAld was reported to protect against Candidiasis and Colitis by promoting interleukin-22 production." (PMID 39511673, 2024). "Conditional deletion of Npm1 in the ILC3 lineage exacerbated colitis and decreased protective IL-22 secretion." (PMID 39103576, 2024). "On the other hand, HIF-1–dependent IL-22 production in group 3 innate lymphoid cells contributes to the protection of C. rodentium–induced colitis." (PMID 39585307, 2024). "The role of IL-22 in Akk’s protective mechanism was further probed using IL-22 knockout (IL-22−/−) mice subjected to DSS-induced colitis." (PMID 39734222, 2024). "In comparison to the MC group, TP2 significantly enhanced the expression of IL-10 (p < 0.0001)and IL-22 (p < 0.05) in the colonic tissues of colitis-induced rats." (PMID 39776580, 2024). "Deletion of IL-23, the IL-23 receptor, or IL-22 itself all result in altered gut microbiome composition and increased sensitivity to chemically induced colitis in mice." (PMID 36894983, 2023). "Meanhwhile we found that B. fragilis promoted IL-22 production, and increased the percentage of IL-22-secreting type 3 innate lymphocytes (ILC3) in colitis." (PMID 37114045, 2023). "Conversely, SCFAs or FFAR2 agonists fed to dextran sulfate sodium (DSS) induced colitis mice can increase the production of ILC3s and IL-22 in the mice colon, which has protective effects on intestinal injury." (PMID 37304260, 2023). "RA signaling pathway prevents and protects against colitis induced by DSS or C. rodentium infection through promoting IL-22 production by ILC3s to form an early immune response." (PMID 37318214, 2023). "Loading TNF-α with GELNs can downregulate NLRP3, caspase-1, IL-1β, TNF-α, IL-6 and IL-1b, upregulate anti-inflammatory substances such as IL-10 and IL-22 in colon tissue of DSS-induced colitis mice." (PMID 37033644, 2023).
colitis (continued). "Our results showed that vmab-mIL22 had potent synergistic anti-inflammatory and repair-promoting activities through blocking the IL17A pathway and activating the IL22 pathway in an influenza and colitis model." (PMID 37189778, 2023). "Especially, urolithin A, a metabolite produced by ellagic acid in the presence of gut microbes, mitigates colitis in IL-22-dependent manner." (PMID 37813835, 2023). "On the other hand, although IL-22 administration resulted in more severe mucosal injury in colitis models, prophylactic treatment with IL-22 in Citrobacter rodentium-induced colitis models ameliorated the intestinal epithelial dysfunction." (PMID 38058517, 2023). "It has also been reported that B. ovatus can produce indole-3-acetic acid and promote interleukin-22 production from immune cells, leading to decreased colonic inflammation in a murine inflammatory bowel disease model." (PMID 36778495, 2023). "The results raised the possibility that IL-22 was responsible for the protective effects of UroA against colitis." (PMID 37813835, 2023). "We found that IL-22-/- mice receiving B. fragilis were more sensitive to DSS-induced colitis than wild-type (IL-22+/+) mice receiving B. fragilis, evidenced by more weight loss, a higher DAI score, a shorter colon length and a higher HAI." (PMID 37114045, 2023). "To gain deeper insights into the mechanism underlying the enhanced barrier function, we next determine if the secretion of IL-22 was necessary for the protective effects of UroA during colitis." (PMID 37813835, 2023). "In our work, we verified that B. fragilis promoted IL-22 production in colon tissue in DSS-induced colitis." (PMID 37114045, 2023). "Altogether, the JAKinib tofacitinib, when provided not too early, is very efficient in limiting clinical signs of DSS-induced colitis and the expression of pro-inflammatory cytokines, while supporting Treg cells, IL-10 and IL-22 expression." (PMID 37275854, 2023). "In contrast, either IL‐22 or an IL‐22‐Fc fusion protein is efficacious in attenuating DSS‐induced colitis in model mice." (PMID 36404603, 2023). "FGF21 deletion protected mice from DSS-induced acute colitis by increasing IL-22 expression-mediated epithelial STAT3 activation, which decreased intestinal inflammation and maintained intestinal goblet cell and Paneth cell homeostasis." (PMID 37432218, 2023). "More importantly, we found the loss in the ability of UroA to induce the reduction of innate lymphoid cells (ILC3s) number after IL-22 neutralization during colitis." (PMID 37813835, 2023). "For example, IL-22 prevents bacterial infections, relieves intestinal inflammation, and restores tissue injury during hepatitis or colitis." (PMID 36825081, 2023). "For example, in ginger-derived extracellular vesicles (G-EVs), miRNA mdo-miR7267-3P induced interleukin-22 (IL-22) production to relieve the symptoms of colitis." (PMID 37759813, 2023). "In fact, urolithin A (UroA), a metabolite transformed from ellagic acid by the gut microbiota, was found to alleviate colitis and enhance gut barrier function in an IL22-dependent manner." (PMID 37813835, 2023). "UroA treatment of DSS colitis experiments was repeated to include a neutralizing antibody against IL-22." (PMID 37813835, 2023). "The stark reduction in bacterial density induced by psyllium argued against a role for IL-22 in mediating its protection against DSS colitis as expression of this cytokine is highly gut microbiota-dependent." (PMID 36828279, 2023). "The oral administration of thinned apple polyphenols attenuated gene expression of IFN-γ, TNF-α, IL-1β, IL-6, IL-17, and IL-22 in the colons of mice with colitis." (PMID 35741912, 2022). "Treatment with FICZ also improved DSS-induced colitis severity in Card9−/− mice and restored colon IL-22 production and antimicrobial peptides." (PMID 36014759, 2022).